SSU72L6 (SSU72 like 6)
Description:
Protein phosphatase that catalyzes the dephosphorylation of the C-terminal domain of RNA polymerase II. Plays a role in RNA processing and termination.
Synonyms: SSU72P8
Gene: Protein-coding gene on chromosome 7 (124,476,317 to 124,477,664, forward strand). Ensembl gene ENSG00000230268.
Subcellular location: Nucleus
Gene Ontology:
Molecular function: protein serine/threonine phosphatase activity; RNA polymerase II CTD heptapeptide repeat phosphatase activity; phosphoprotein phosphatase activity
Biological process: termination of RNA polymerase II transcription; mRNA 3'-end processing; mRNA processing; regulation of transcription by RNA polymerase II
Cellular component: mRNA cleavage and polyadenylation specificity factor complex; nucleus
Homologues: Orthologues: chimpanzee SSU72L6 (98% identical), tropical clawed frog ssu72 (66% identical), zebrafish ssu72 (66% identical), Drosophila melanogaster Ssu72 (50% identical), Caenorhabditis elegans ssup-72 (46% identical). Paralogues in human: SSU72L4 (94% identical), SSU72L1 (93% identical), SSU72L2 (93% identical), SSU72L3 (93% identical), SSU72L5 (93% identical), SSU72 (70% identical).